PTH (parathyroid hormone)
Diseases named in the same sentence as PTH in open-access papers (continued):
Sharing a sentence is not in itself a finding about the gene and the disease.
tumor (continued). "It is possible that PTH induces modification of the vascular niches outside the long bones, with implications for bone remodeling, tumour cell location, mobility and proliferation." (PMID 30261597, 2018). "We analyzed a limited number of ribs (n = 3 control and n = 3 PTH) by 2-photon microscopy to determine if tumour cell homing differed at this site." (PMID 30261597, 2018). "Effects of PTH on the bone microenvironment and tumour cell colonization and growth was analyzed using bioluminescence imaging, two-photon microscopy, and histological analysis." (PMID 30261597, 2018). "As the lifespan of osteoblasts in mice is estimated to be around 12 days, their number would remain increased following PTH treatment during the key period of tumour cell homing and colonization of the bone metastatic niche in our model." (PMID 30261597, 2018). "Patients with cystic parathyroid adenomas had higher serum intact parathyroid hormone and calcium levels, larger maximum tumor diameter, and lower serum inorganic phosphorus level than did those with solid adenomas." (PMID 30123260, 2018). "The most intriguing finding in our study is that PTH appeared to exert differential effects on tumour growth depending on the skeletal site." (PMID 30261597, 2018). "In contrast, there were significantly higher numbers of tumours detected in other sites in PTH-treated mice vs. control (mean numbers of tumours/mouse in 40 μg/kg PTH: 3.86 vs. control: 1.29, p < 0.001, 80 μg/kg PTH: 3.75 vs. control: 1.29, p < 0.001)." (PMID 30261597, 2018). "All patients show elevated serum calcium and PTH levels, larger tumor size, and vascular and capsular invasion." (PMID 30290620, 2018). "For asymptomatic individuals (e.g., family members) the following is recommended: periodic biochemical screen (serum total calcium and PTH): tumor surveillance, e.g., panoramic jaw x-ray, kidney and uterine ultrasound." (PMID 28774260, 2017). "Runx2 expression has a pro-survival role in rapidly proliferating tumor cells in the bone microenvironment by promoting PTH or PTHrP mediated antiapoptototic effect and inducing the expression of survivin." (PMID 28300755, 2017). "Mice were aged to 18-21 months and studied for survival, tumour development and proliferation, and serum biochemistry, and compared to age-matched wild-type (Cdc73+/+ and Cdc73+/+/PTH-Cre) littermates." (PMID 28288139, 2017). "Several studies have shown that tumor weight is the main determinant of patients’ PTH and calcium levels." (PMID 28855268, 2017). "The tumor mass and calcium levels were partially controlled (2.61 mmol/L), whereas the PTH concentration remained low (19 ng/mL)." (PMID 28977163, 2017). "Tumor extracts contained a biologically-active protein, slightly larger than PTH, yet had similar activity to PTH." (PMID 29056680, 2017). "To elucidate the mechanisms responsible for PTH-mediated tumour resistance, we also conducted skin carcinogenesis experiments with Pth knockout (Pth−/−) mice." (PMID 28894263, 2017). "This would to some degree explain thelack of spatial correlation between tumor PTH mRNA and protein levels." (PMID 26865585, 2016). "Tumor PTH content was measured by immunohistochemistry (IHC), and PTH geneexpression by chromogenic in situ hybridization (CISH)." (PMID 26865585, 2016). "Some, but not all, studies have reported variouscorrelations between patient vitamin D levels and disease severity (PTH levels, tumor weight,bone turnover)." (PMID 26865585, 2016). "PTH abundance was modestly suppressed by high calcium conditions in two of the three tumors (1.23-fold and 1.20-fold decrease), with a third tumor demonstrating a greater degree of responsiveness (2.70-fold reduction in PTH)." (PMID 27537691, 2016). "If PTHimmunoreactivity reflects the tumor calcium–PTH set point, our data imply that the maindeterminant of disease severity should be tumor weight." (PMID 26865585, 2016).
tumor (continued). "Clinical history, tumor location, and high levels of PTH in the aspirated material support the diagnosis of primary parathyroid lesions." (PMID 28003924, 2016). "Weaker tumor PTH mRNA level was significantlyassociated with higher concentration of circulating 25-hydroxyvitamin D (P =0.005)." (PMID 26865585, 2016). "While observational, our study suggests that circulating 25(OH)D3 levelsmay influence tumor PTH expression in a clinical setting, but further studiesare required to assess the possible gains of vitamin D supplementation in pHPT." (PMID 26865585, 2016). "The rate of intraoperative PTH decline in vivo following tumor excision appeared to correspond to relative calcium suppressibility." (PMID 27537691, 2016). "When released by the tumor into the circulation, the protein, which shares sequence homology with parathyroid hormone (PTH), activates PTH receptors to promote release of calcium from bone and its retention in the kidney." (PMID 25852647, 2015). "Parathyroid hormone-related protein (PTHrP), isolated from the tumor tissues of Malignancy-associated hypercalcemia (MAH) patients, was reported to be credited for its ability to mimic parathyroid hormone (PTH)." (PMID 26597083, 2015). "In vivo, dearth of CaSR significantly increased expression of proliferation markers and decreased levels of differentiation and apoptotic markers in the colons of CaSR/PTH double knock-out mice confirming the tumor suppressive functions of CaSR." (PMID 25701758, 2015). "The immunohistochemical finding of PTH protein in the tumor confirms its parathyroid origin as well as its ability to transcribe the PTH mRNA." (PMID 26350418, 2015). "Nonetheless, the anti-tumor effects of PTH provide proof-of-principal for the use of bone-anabolic agents against myeloma bone disease and osteolytic breast metastases." (PMID 25757219, 2014). "The tumor is secondary to localized rapid osteoclastic bone turnover resulting from the direct effect of PTH." (PMID 23251174, 2012). "In the present study, we tested the effect of a relatively high dose of PTH (80 μg/kg/d) on MM bone disease and tumor growth in our animal models." (PMID 21188144, 2010). "For this set of experiments, cells from the same patient were injected into two mice, and the host with higher hIg levels (indicative of higher tumor burden) received PTH treatment, while the other received saline treatment." (PMID 21188144, 2010). "Although PTH treatment had heterogeneous effects on MM growth, the overall tumor burden (final hIg levels) was significantly lower (p<0.04) in PTH-treated hosts than in saline-treated hosts." (PMID 21188144, 2010). "Intraoperative PTH (IPTH) measurement is an emerging technique for optimizing tumour removal while minimizing the invasiveness of parathyroid surgery." (PMID 16504029, 2006). "Immunohistochemical staining for PTH revealed strong cytoplasmic positivity in the tumor cells, which was instrumental in confirming the diagnosis of metastatic parathyroid carcinoma." (PMID 16569241, 2006). "This so called 'bone hunger syndrome' is further confirmed by the finding that in the subgroup of blastic appearances CaCr diminished whereas both ICTP and PTH increased according to the extent of tumour load in the bone." (PMID 8664134, 1996). "For example, increased secretion of parathyroid hormone, stimulated in osteoblasts by interactions with tumor cells, promotes differentiation of osteoclasts that degrade bone matrix creating a mechanically softer microenvironment that is rich in soluble factors to promote additional tumor growth." (PMID 41579220, 2026). "Significant differences in serum calcium level (P = 0.020), serum PTH level (P = 0.039), total 25-hydroxyvitamin D level (P = 0.008), and tumour diameter (P = 0.013) were found between patients with initial tumours and patients with recurrent tumours." (PMID 40525887, 2025).
tumor (continued). "Although the presence of the chimeric transcript strongly suggests transcriptional activation of PTH in the tumor, the actual expression of functional PTH protein and activation of downstream signaling pathways remain speculative." (PMID 40641561, 2025). "These biological effects suggest that aberrant PTH expression in tumor cells could contribute to the fibro-osseous characteristics of the tumor, potentially by promoting fibrous matrix production, increased vascularity, and altered bone metabolism." (PMID 40641561, 2025). "Imatinib normalized calcium and parathyroid hormone levels and induced tumor regression." (PMID 41479802, 2025). "By directly interfering with the PTH/PTHrP axis, the bone-targeted antagonists in the present study could have disrupted tumor-stromal interactions essential for metastatic colonization and osteolysis." (PMID 40941030, 2025). "Despite the low expression, the detection of PTH mRNA supported a parathyroid origin of the tumor." (PMID 40762649, 2025). "Given that cancer-type APTs were associated with larger tumor size and lower BMD, we examined whether tumor size and BMD were correlated with serum PTH levels." (PMID 40434298, 2025). "The recurrent tumor showed weak and patchy, but retained immunohistochemical PTH expression." (PMID 40762649, 2025). "Together, these experimental data and the observations of our study suggest that higher and elevated PTH levels could alter the fate of tumor cells and the release of leukemic stem cells from the bone marrow, thereby affecting EFS." (PMID 39141058, 2024). "PTH expression is almost exclusive to parathyroid tissues rather than thyroid tissue, facilitating the differential diagnosis of the histological origin of the tumor." (PMID 39054438, 2024). "This is due to the ability of the tumor cells to synthesize the parathyroid-hormone-related polypeptide (PTH-rp), which has a similar amino acid sequence and function as the parathyroid hormone (PTH)." (PMID 39728969, 2024). "Previous studies have suggested that if the tumour can be felt, maximum tumour diameter exceeds 3 cm, total plasma calcium level exceeds 3.5 mmol/L, and blood PTH level is 10 times higher than the upper limit of the normal value, the tumour is likely to be a PTC." (PMID 37403167, 2023). "Interestingly, though, while PTH increases BMD in the radial shaft, it does not increase BMD in the distal radius, and in the second PTH preclinical study, this is where tumor burden was increased." (PMID 37345007, 2023). "However, if a surgeon is uncertain about the targeted tumor, measurement of intraoperative PTH levels for a more precise surgery would be helpful." (PMID 37341946, 2023). "The clinical symptoms of patients with PC are mainly related to whether the tumor secretes parathyroid hormone (PTH)." (PMID 38019325, 2023). "The PTH studies suggest that PTH/PTHrP may have differential effects on tumor cell seeding in distinct skeletal niches, but this is only partially supported by the clinical data." (PMID 37345007, 2023). "Immunohistochemically, the tumor was positive for PTH-rerated protein and was diagnosed as an EMPA." (PMID 35987641, 2022). "Only 2 months later, PTH increased to 184.6 pg/ml, and radiotherapy was carried out in our hospital from April to June 2019 (50 Gy/25 times in the left anterior cervical region and 60 Gy/30 times, 2 Gy/time, 5 times/week in the tumor bed region)." (PMID 36303876, 2022). "However, distinguishing PTC from PTH and solitary nodules with papillary-like nuclear change is challenging due to tumor heterogeneity." (PMID 34934597, 2021). "It has been documented that PTH is a tumor promoter acting as a co-mitogen and anti-apoptotic factor, which may further stimulate cell proliferation and intensively suppress apoptosis of cells." (PMID 34380458, 2021). "The tumor secretes an abundance of parathyroid hormone (PTH) resulting in elevated calcium levels." (PMID 32643039, 2020).
tumor (continued). "Her serum calcium and intact PTH levels were normal from 15 min after tumor resection." (PMID 31727048, 2019). "Furthermore, we show that SST5 expression correlates with the tumor Ki-67 proliferation index, as well as with the circulating calcium and PTH concentrations." (PMID 31336364, 2019). "In addition, the brief period of PTH treatment (five days) was completed prior to injection of tumour cells in the animals, thus avoiding any direct effects of PTH on tumour growth." (PMID 30261597, 2018). "Administration of PTH may modify tumour cells themselves, precluding identification of the specific effects on the osteoblastic niche." (PMID 30261597, 2018). "The present study is the first to show that intermittent PTH not only increases the number of tumour cells in different skeletal sites, but also results in increased numbers of overt tumours developing long after the PTH effects on bone have reverted to control levels." (PMID 30261597, 2018). "However, animals pre-treated with PTH had a significantly higher number of tumour colonies distributed throughout skeletal sites outside the hind limbs." (PMID 30261597, 2018). "In future studies, we will establish the effects of short-term PTH treatment on both osteoblasts and the vasculature in different skeletal sites and map whether subsequent tumour cell homing is modulated." (PMID 30261597, 2018). "In addition, there was a differential distribution of skeletal tumours, with PTH-pretreated animals having tumours in ribs, hip, vertebrae, skull and front limbs, whereas control animals almost exclusively had tumours in the hind limbs." (PMID 30261597, 2018). "Thus, osteoblast-generated growth factors enhance PTH-rP production, creating a vicious cycle where bone resorption and tumor growth reciprocally enhance each another." (PMID 28750038, 2017). "Further studies suggest PHTR1 may exert the tumor-promoting effects through being activated by its ligands, including parathyroid hormone (PTH) and parathyroid hormone-related peptide (PTHrP)." (PMID 29121993, 2017). "PTH, 1,25 OH vitamin and calcitonin levels, as well as the tumor size, remained unchanged." (PMID 28977163, 2017). "Circulating PTH levels in the two patients (PT 1, PT 2) whose tumors demonstrated less sensitivity to calcium suppression declined at a slower rate than in the patient with a more responsive tumor (PT 3)." (PMID 27537691, 2016). "Future genetic studies may be able to cluster and correlate geneticaberrations to the level of tumor PTH secretion and clinical phenotype." (PMID 26865585, 2016). "Low tumor PTH mRNA level was significantly associated with low tumor PTHimmunoreactivity (P = 0.026), but the two did not correlate with regard tohistological distribution within individual tumors." (PMID 26865585, 2016). "Given that both PTH and PTHrP bind to the same receptor, the PTH/PTHrP receptor, PTHrP from tumor cells may stimulate stromal/osteoblastic cells to secrete EVs, and thus the EVs may induce osteoclast differentiation." (PMID 26343739, 2015). "Moreover, many of the chemokines, cytokines, hormones, and growth factors produced by tumor cells are able to induce an increase in RANKL expression through PTH-rP, and a decrease in OPG production, thus aggravating the vicious cycle in bone metastases." (PMID 26779435, 2015). "Previous studies have suggested vitamin D to have anti-proliferative effects on tumor cells, whereas PTH may have carcinogenic effects." (PMID 24952509, 2014). "Therefore, we first noticed that through dependence on primary cilia, PTH can achieve its facilitation function and regulate ciliogenesis oppositely, eventually affecting the proliferation and invasion activity of tumor cells." (PMID 25365173, 2014).
tumor (continued). "Tumor production of factors including parathyroid hormone (PTH), PTH-related peptide (PTHrP) and interleukins (IL)-1, IL-6 and IL-11 stimulate the production of the cytokine, receptor activator of nuclear factor-KB ligand (RANKL), by osteoblasts and stromal cells." (PMID 26237143, 2013). "In some cases it may be related to direct the secretion of PTH by tumor-RP (parathyroid hormone-related protein) detected by immunohistochemistry." (PMID 23346438, 2012). "Thus, a vicious cycle exists in bone between production by the tumor cells of mediators such as PTH-rP and subsequent production by bone of growth factors such as TGF-beta, which enhance PTH-rP production." (PMID 23243441, 2012). "The effects of PTH pretreatment on tumor progression were examined in SCID-rab mice." (PMID 21188144, 2010). "Our results provide evidence that PTR-4 peptide-pulsed autologous DC may break the tolerance of human TIL against the autologous tumour by inducing a PTH-rP-specific CTL immune reaction." (PMID 11742494, 2001). "Additional sequencing of PTH in the tumor revealed no somatic mutations." (PMID 40762649, 2025). "PTH or a similar hormone might be induced by prostate and other types of tumor cells." (PMID 39200986, 2024). "Thus, we speculated that the higher consumption of calcium in the evening might moderately decrease the secretion of PTH and reduce the chance of malignant proliferation of tumor cells." (PMID 34380458, 2021). "They further indicated that PTH administration retained its beneficial effect on tumor metastasis by increasing bone formation, decreasing osteoclast formation, and significantly reducing tumor engraftment and tumor burden of both murine and human BrCa cells in the mouse intratibial models." (PMID 30151009, 2018). "In addition, PTH may be a tumour promoter acting as a co-mitogen and anti-apoptotic factor directly." (PMID 28665326, 2017). "Since a progression of PA to PC has been suggested in some earlier publications, higher Ca as well as PTH levels in LAT cohort when compared to GER patients with PHPT, in association with higher PC frequency, could have been interpreted as an evidence of tumour progression." (PMID 26658808, 2016). "Circulating 25-hydroxyvitamin Dlevels may influence tumor PTH expression in vivo." (PMID 26865585, 2016). "Indeed,tumors with lower PTH mRNA levels, as measured by CISH, were significantlyassociated with lower PTH immunoreactivity, suggesting that reduced PTH expression may partlyexplain the decreased tumor PTH levels in these cases." (PMID 26865585, 2016). "Speculatively, a genetic event resulting in parathyroidproliferation while leaving PTH-regulatory systems intact – in this case exemplified byintact CASR expression – could account for a phenotype with relativelylarger tumor size and lower PTH expression per tumor cell." (PMID 26865585, 2016). "It is unknown whether sustained excess PTH secretion in bone metastatic patients reflects poor clinical conditions independently of therapy, or whether it has a role in the disease progression due to direct or indirect effects on tumour growth." (PMID 18506177, 2008). "In fact, the endogenous PTH-rP epitope peptide levels could be too poor to be detected by the CTLs that are conversely able to recognise in vitro the same antigen overexpressed on tumour cells." (PMID 12838324, 2003). "Furthermore, mRNA for the PTH/PTHrP receptor was detected in all samples, thus the PTHrP produced by these tumours may potentially act in an autocrine or paracrine fashion." (PMID 7669584, 1995). "Both HHM and HPT are characterized by the increased osteoclast-mediated bone resorption driven by the following humoral factors: parathyroid hormone (PTH) in HPT and tumor-derived PTHrP in HHM." (PMID 41561737, 2025).